CACNA1D (calcium voltage-gated channel subunit alpha1 D)
Diseases named in the same sentence as CACNA1D in open-access papers (continued):
Sharing a sentence is not in itself a finding about the gene and the disease.
gastric cancer (10 papers, 2020 to 2025). A primary or metastatic malignant neoplasm involving the stomach. "further confirmed that a miRNA-like t016 suppressed hyperactivation of MAPK signaling through downregulating the expression of CACNA1d gene, thereby inhibiting gastric cancer cell proliferation." (PMID 41415269, 2025). "This downregulation affects the MAPK signaling pathway by modulating the expression of CACNA1d, thereby inhibiting the proliferation of gastric cancer cells." (PMID 40649749, 2025). "In gastric cancer studies, it was found that CACNA1D was regulated by tRNA derivatives to participate in MAPK signaling pathway transmission, inhibiting the growth and metastasis of tumor cells." (PMID 38329437, 2024). "TRF‐Val‐CAC‐016, a tsRNA molecule with significantly down‐regulated expression in gastric cancer tissues, inhibits the proliferation of gastric cancer cells by regulating the CACNA1D‐mediated MAPK signalling pathway." (PMID 39365143, 2024). "tRF-Val-CAC-016 modulates the transduction of CACNA1d-mediated MAPK signaling pathways to suppress the proliferation of gastric carcinoma." (PMID 35590368, 2022). "Besides, tRF-Val-CAC-016 modulates the transduction of CACNA1d-mediated MAPK signaling pathways to suppress the proliferation of gastric carcinoma." (PMID 35590368, 2022). "Therefore, we hypothesize that tRF-Val-CAC-016 modulates the transduction of CACNA1d-mediated MAPK signaling pathways to suppress the proliferation of gastric carcinoma." (PMID 35590368, 2022). "Subsequently, the results of immunoblotting assays related to the MAPK signaling pathway were consistent with our hypothesis that tRF-Val-CAC-016 modulates the canonical MAPK signaling pathways by targeting CACNA1d to influence the proliferation of gastric carcinoma." (PMID 35590368, 2022). "Notably, tRF-Val-CAC-016 markedly inhibits the proliferation of gastric carcinoma cell lines, regulating the classic MAPK signaling pathway by targeting Calcium Voltage-Gated Channel Subunit Alpha1 D (CACNA1d) and suppressing gastric carcinoma proliferation." (PMID 39659673, 2024).
cardiac arrhythmia (9 papers, 2017 to 2025). Any disturbances of the normal rhythmic beating of the heart or MYOCARDIAL CONTRACTION. "Mutations in LTCC genes, including CACNA1C, CACNA1D, CACNB2 and CACNA2D, will induce the dysfunctions of calcium channels, which result in the abnormal excitations of cardiomyocytes, and finally lead to cardiac arrhythmias." (PMID 30027834, 2018). "An NGS-Panel for Arrhythmias (48 genes; performed at the Department of Clinical Genetics, University of Amsterdam in 2015) detected two heterozygous variants of uncertain significance (class 3 variants): c.647C > T; (p.Ser216Leu) SCN5A and c.3374C > T; (p.Ala1125Val) in CACNA1D." (PMID 37269378, 2023).
type 2 diabetes (9 papers, 2016 to 2025). "Polymorphisms in CACNA1D are also associated with type 2 diabetes, linked to diastolic and systolic blood pressure, and ototoxicity." (PMID 31796056, 2019). "The L-type voltage-gated Ca2+ channel genes Cacna1c and Cacna1d are essential for rodent pancreatic beta cell function and polymorphisms in Cacna1d have been associated with type 2 diabetes." (PMID 26518685, 2016). "CaV1.3 is important in human glucose‐induced insulin secretion and common variants of CACNA1D may be associated with type 2 diabetes mellitus." (PMID 39365143, 2024). "Decreased expression of calcium channel-related genes such as cacna1c and cacna1d is one of the characteristics of type 2 diabetes." (PMID 34358068, 2021). "Three of the GWAS genes (SLC2A9, CACNA1D and CSMD1), one in the chromosome 12 and two in the chromosome 16 synteny groups, harboured SNPs significantly associated with both blood pressure and insulin resistance/type 2 diabetes in humans." (PMID 28130354, 2017).
bipolar disorder (7 papers, 2015 to 2025). A disorder of the brain that causes unusual shifts in mood, energy, activity levels and the ability to carry out day-to-day tasks. "Genes encoding calcium channels, such as RYR1 and CACNA1D, have been identified as risk loci for bipolar disorder due to their roles in calcium signaling and the regulation of circadian rhythms." (PMID 40430072, 2025). "The CACNA1D gene encoding the CaV1.3 has been identified as a risk gene for bipolar disorder." (PMID 35209100, 2022). "In addition, genetic data identify CACNA1D as being a risk factor for bipolar disorders." (PMID 35209100, 2022).
Bradycardia (7 papers, 2015 to 2024). A slower than normal heart rate (in adults, slower than 60 beats per minute). "Moreover, patients with a mutation in the CACNA1D gene, which encodes the pore-forming α1 subunit of Cav1.3, experience pronounced bradycardia in 12–24-h ECG recordings, and their HRV time-domain indices are increased." (PMID 25755643, 2015). "A homozygous 3-bp insertion in CACNA1D, inducing p.G403_404ins, was first screened from a Pakistani family with pronounced bradycardia." (PMID 30027834, 2018).
schizophrenia (7 papers, 2015 to 2025). A major psychotic disorder characterized by abnormalities in the perception or expression of reality. "In the brain, voltage-gated calcium channel subunit alpha 1C (CACNA1C), Cav1.2, and CACNA1D, Cav1.3 (common variants in CACNA1C and CACNA1D identified with BD, MDD, or schizophrenia), are the predominant L-type Cav channels and are expressed in various cell types including NPC." (PMID 32425815, 2020).
channelopathies (6 papers, 2016 to 2023). "The CACNA1D gene is also expressed in the AV node, meaning any variants have implication for Cav1.3-related channelopathies in the AV node." (PMID 37025382, 2023). "Initially, no known human channelopathies were described for Cav1.3 channels or its associated CACNA1D gene." (PMID 37025382, 2023).
Timothy syndrome (6 papers, 2015 to 2024). "Given the nature of the mutation, the severe congenital disorder in two other patients, and the pathophysiologic relationship to Timothy syndrome, our data strongly suggest possibly a causal role of CACNA1D gain-of-function mutations for ASD in these patients." (PMID 25620733, 2015).
adrenal adenomas (5 papers, 2015 to 2025). "Somatic mutations of CACNA1D are among the most frequent mutations in aldosterone-producing adrenocortical adenomas, particularly in the absence of KCNJ5 mutations, where the gain of function of Cav1.3 is responsible for aldosterone production." (PMID 40540150, 2025).
Alzheimer disease (5 papers, 2016 to 2024). A progressive, neurodegenerative disease characterized by loss of function and death of nerve cells in several areas of the brain leading to loss of cognitive function such as memory and language. "In the Alzheimer’s disease pathway, we found genes up-regulated (Apbb1, Atf6, Cacna1d, Calm3, Casp7, Itpr1, Lpl, and Ppp3ca) and down-regulated (Aph1b, Bid, Cycs, Fadd, Fas, and Nae1)." (PMID 28513549, 2017).
developmental delay (5 papers, 2019 to 2023). "Here, we report a 4-week-old new-born with the novel de novo missense variant F747S with a so far not described prominent jittering phenotype in addition to symptoms previously reported for CACNA1D mutations including developmental delay, elevated aldosterone level and transient hypoglycemia." (PMID 36208199, 2023).
sinoatrial node dysfunction and deafness (5 papers, 2018 to 2025). "Loss-of-function variants in CACNA1D are responsible for a Mendelian disorder known as SANDD (SinoAtrial Node Dysfunction and Deafness, MIM Number: 614896), which follows an autosomal recessive inheritance pattern." (PMID 40758722, 2025).
Hyperglycemia (4 papers, 2017 to 2024). An increased concentration of glucose in the blood. "CACNA1D is involved in the regulation of blood pressure, and alterations in CACNA1D methylation have been observed in neonates exposed to maternal hyperglycemia." (PMID 38886689, 2024).
ovarian carcinoma (4 papers, 2020 to 2024). A malignant neoplasm originating from the surface ovarian epithelium. "CACNA1D is important for maintaining the stemness of ovarian cancer stem cells (CSCs) and is associated with poor prognosis in patients with ovarian cancer." (PMID 39365143, 2024). "Therefore, CACNA1D has the potential to become a biomarker and therapeutic target for recurrence and metastasis in patients with advanced ovarian cancer." (PMID 39365143, 2024). "Mutations of CACNA1D and BIRC6 in ovarian cancer were first reported in our study." (PMID 36081665, 2022). "Moreover, the Spearman correlation was analyzed to see if L- and T-type calcium channel genes (CACNA1D, CACNA1F, and CACNA1H) were correlated with the expression of stem cell markers in the ovarian cancer patients (GSE53963 and GSE14764)." (PMID 32230901, 2020). "Next, we questioned whether the expression of three L- and T-type calcium channel genes (CACNA1D, CACNA1F, and CACNA1H) correlates with the survival of ovarian cancer patients." (PMID 32230901, 2020). "BKCa and calcium channels may be a suitable pharmacological target for treating recurrence and drug resistance in late-stage ovarian cancer patients who exhibit amplification of the KCNMA1 gene and calcium channel subunits genes (CACNA1D, CACNA1F, and CACNA1H)." (PMID 33923707, 2021).
familial hyperaldosteronism (3 papers, 2019 to 2021). "Somatic mutations in four genes (KCNJ5, ATP1A1, ATP2B3 and CACNA1D) have been identified in nearly 60% of the sporadic APAs, while germline mutations in KCNJ5 and CACNA1H have been reported in different subtypes of familial hyperaldosteronism." (PMID 34829937, 2021). "Rare germline variants of CYP11B2 (encoding aldosterone synthase), CLCN2 (encoding voltage-gated chloride channel ClC-2), KCNJ5, CACNA1H (encoding a subunit of T-type voltage-gated calcium channel CaV3.2), and CACNA1D have been reported in different subtypes of familial hyperaldosteronism." (PMID 31695023, 2019).
lung cancer (3 papers, 2017 to 2024). A malignant neoplasm involving the lung. "The active ingredient of golden‐flowered tea may inhibit non‐small cell lung cancer with epidermal growth factor receptor mutations by targeting CACNA1D, offering new possibilities for the treatment of small cell lung cancer." (PMID 39365143, 2024). "For example, clinical studies have demonstrated overexpression of CACNA1D (Cav1.3) (L type), CACNA1A (Cav2.1) (P/Q type), and CACNA1G (Cav3.1) (T type) in lung cancer, and overexpression of CACNA1A (Cav2.1) was associated with poor prognosis." (PMID 28127114, 2017).
bladder cancer (2 papers, 2016 to 2021). "No reports are present in literature referring CACNA1D direct link to bladder cancer." (PMID 27716384, 2016).
cardiac hypertrophy (2 papers, 2020 to 2022). "Cardiac hypertrophy is associated with alterations in calcium handling and hence, it is reassuring that genes encoding for proteins involved in calcium handling and signaling (CACNA1D, CACNA1G, CACNA1S or CASC2) also show differential expression at all time points in our model." (PMID 32878883, 2020).
epileptic seizures (2 papers, 2021 to 2022). "In some human CACNA1D mutation carriers, different types of seizures have been observed (focal and/or generalised seizures)." (PMID 33057948, 2021).
glioblastoma (2 papers, 2021 to 2023). The most malignant astrocytic tumor (WHO grade IV). "There was no expression of the cacna1d gene in the U87 glioblastoma line even in the control sample." (PMID 33419226, 2021).
Insulin resistance (2 papers, 2017 to 2021). Increased resistance towards insulin, that is, diminished effectiveness of insulin in reducing blood glucose levels. "CACNA1D encodes a voltage-dependent calcium channel, and SNPs in this gene are associated by GWAS with insulin resistance in African Americans, and with blood pressure in Chinese and people of African ancestry." (PMID 28130354, 2017). "CSMD1 encodes the cub and sushi domains 1 protein and, as for CACNA1D, SNPs in this gene are associated with insulin resistance in African Americans, and with blood pressure in the Han Chinese population." (PMID 28130354, 2017). "Then, we assessed the expression of an upregulated gene map2k6 and downregulated genes cacna1c and cacna1d by insulin resistance." (PMID 34358068, 2021). "Three genes, SLC12A9 (chromosome 12), CACNA1D and CSMD1 (chromosome 16), were associated with both blood pressure and insulin resistance-related metabolic traits." (PMID 28130354, 2017). "In contrast, the expression of the cacna1c and cacna1d genes is decreased by insulin resistance." (PMID 34358068, 2021).
insulinoma (2 papers, 2015 to 2026). "Nonetheless, the present results are consistent with very recent findings showing decreased expression of the voltage-gated calcium channel subunits including Cacna1d in rat insulinoma-derived INS1 β cells silenced for Tcf7l2." (PMID 25355422, 2015).
mood disorder (2 papers, 2019 to 2025). A cognitive disorder a disturbance in which the person's mood is hypothesized to be the main underlying feature. "Recent studies have identified genetic variants linked to both mood disorders and cardiometabolic conditions, including CACNA1D, FTO, BDNF, POMC, IGF." (PMID 39834212, 2025).
Obesity (2 papers, 2025). Accumulation of substantial excess body fat. "Blood pressure control after adrenalectomy tends to be better in women.Patients who harbour KCNJ5 mutations have better clinical outcomes after surgery.Patients who harbour CACNA1D mutations have worse clinical outcomes after surgery.Men have higher rates of obesity than women." (PMID 40296186, 2025).
pancreatic cancer (2 papers, 2016 to 2021). "A novel 14-gene signature comprising CCDC148, SH3RF2, CACNA1D, POLD3, PARP1, AP1M2, C4orf19, ANO1, VGLL1, SCEL, INPP4B, NET1, INSIG2 and BVES and a corresponding risk score formula were established for pancreatic cancer risk stratification and prognosis prediction." (PMID 33731794, 2021).
adrenal hyperplasia (1 paper, 2025). "In addition, somatic mutations in CACNA1D, the gene that encodes the α-1D subunit of a voltage-dependent L-type Ca2+ channel, have been identified as the most common drivers of Aldo autonomy in micronodules associated with bilateral adrenal hyperplasia." (PMID 41091658, 2025).
aldosteronomas (1 paper, 2022). "In 2013 after KCNJ5 discovery, somatic CACNA1D gain-of-function variants were reported in aldosteronomas, with a prevalence of around 10%." (PMID 35813615, 2022). "KCNJ5 somatic variants are predominant among aldosteronomas (classical histology), whereas CACNA1D is the most frequent mutated gene in APMs." (PMID 35813615, 2022). "Aldosteronomas are a major cause of unilateral PA, associated with somatic variants in KCNJ5, CACNA1D, ATP1A1, ATP2B3, CLCN2, CACNA1H and CTNNB1 genes." (PMID 35813615, 2022).
aortic insufficiency (1 paper, 2022). "Recently, the use of exome sequencing allowed the detection of a single CACNA1D (encoding for the L-type voltage-gated calcium channel) activating mutation in a syndromic child with neurodevelopmental delay, aortic insufficiency and HI requiring diazoxide therapy." (PMID 35422763, 2022).
chronic kidney disease (1 paper, 2024). Impairment of the renal function secondary to chronic kidney damage persisting for three or more months. "Furthermore, genes that have been implicated in chronic kidney disease (CKD), such as Slc6a6 were up-regulated in ECs, and Umod, Cacna1d, Ddx1 were specifically up-regulated in PTs." (PMID 38641839, 2024).
hypertrophic cardiomyopathy (1 paper, 2024). A condition in which the myocardium is hypertrophied without an obvious cause. "CACNA1D, MYH6 and SCN10A had a cardiovascular disease as their top disease association (sinoatrial node dysfunction, hypertrophic cardiomyopathy and AF, respectively)." (PMID 38969939, 2024).
invasive lobular breast carcinoma (1 paper, 2015). An infiltrating lobular adenocarcinoma of the breast. "The TCGA and PNAS databases indicated that CACNA1D was significantly overexpressed relative to normal tissue in invasive lobular breast carcinoma with invasive ductal and lobular carcinoma, which again implies that patients with high expression of CACNA1D were likely to develop those diseases." (PMID 26147197, 2015).
leiomyoma (1 paper, 2023). A well-circumscribed benign smooth muscle neoplasm characterized by the presence of spindle cells with cigar-shaped nuclei, interlacing fascicles, and a whorled pattern. "Our data, demonstrating decreased expression of S100A4 and S100A1 particularly in mutated tumors and the increase in CACNA1D expression, suggest potential reduced binding of calcium and greater calcium entry into leiomyoma cells which could contribute to tumor calcification." (PMID 36835153, 2023). "This analysis indicated that the expression of WNT16, CACNA1D, DCX, and WIF1 was significantly higher, while the expression of MTMR8 was significantly lower in myometrium adjacent to MED12-mutated leiomyomas compared to myometrium adjacent to MED12 wild-type leiomyomas." (PMID 36835153, 2023).
metastatic disease (1 paper, 2019). "The observed overexpression of CACNA1A, CACNA1C, and CACNA1D suggests that they are likely targets for cancer treatment, as blockage or partial inhibition of their expression could help to modulate the progression of metastatic disease." (PMID 31416476, 2019).
myopia (1 paper, 2019). "Validation of the role of KCNMA1 in myopia progression is needed, particularly in ion channel activity which is one of the major functional pathways implicated, with an existing pool of several associated genes (KCNQ5, KCNJ2, and CACNA1D)." (PMID 31415580, 2019).
nicotine addiction (1 paper, 2017). "Given the key role of this receptor in the mechanism of addiction, it is possible that any sex-related variation in CACNA1D expression may be reflected in corresponding differences in susceptibility to nicotine addiction." (PMID 28225026, 2017).
non-small cell lung carcinoma (1 paper, 2023). A group of at least three distinct histological types of lung cancer, including non-small cell squamous cell carcinoma, adenocarcinoma, and large cell carcinoma. "Furthermore, we found other pleiotropic genes as drug targets for lung and GIT diseases, such as pralsetinib targeting DDR1 for the treatment of non-small cell lung cancer and trimebutine targeting CACNA1D for the treatment of IBS." (PMID 38102678, 2023).
prostate hyperplasia (1 paper, 2024). "CACNA1D is primarily related with the cell cycle, potentially impacting the development of prostatic hyperplasia cells through cell cycle regulation." (PMID 39703506, 2024). "ROC curves were then used to assess the predictive potential of these key gene markers in prostate enlargement, revealing AUC values of 0.885, 0.874, 0.885, and 0.874 for DACH1, CACNA1D, STARD13 and RUNDC3B, respectively." (PMID 39703506, 2024). "To delve deeper into the potential mechanisms of DACH1, CACNA1D, STARD13, and RUNDC3B in regulating prostate hyperplasia, we stratified prostate hyperplasia samples according to the levels of expression of these genes and conducted GSEA." (PMID 39703506, 2024).
renal carcinoma (1 paper, 2021). A carcinoma arising from the epithelium of the renal parenchyma or the renal pelvis. "CACNA1D (Voltage-dependent L-type calcium channel subunit alpha-1D) is lowly expressed in RCC, and the expression level of CASP9 (Caspase-9) is altered in RCC by rs12124078 SNP, while CTSG (Cathepsin G) inhibition enhances apoptosis in human renal carcinoma (Caki) cells." (PMID 33573278, 2021).